VEGFC (vascular endothelial growth factor C)
Diseases named in the same sentence as VEGFC in open-access papers (continued):
Sharing a sentence is not in itself a finding about the gene and the disease.
cancer (continued). "In addition, β-adrenergic receptor signaling promotes the macrophage expression of COX2 and increases the secretion of PGE2, which thereby activates the release of cancer-derived VEGFC to facilitate metastasis." (PMID 35338118, 2022). "In situ and transgenic models of breast cancer, stress promotes the release of norepinephrine in the nervous system and activates the release of cancer-derived VEGFC to promote lymphangiogenesis and remodeling, and it also increased the expression of VEGFR3(FLT4) in stoma cells." (PMID 35338118, 2022). "However, LEDGF/p75 can activate the expression of cancer-related genes e.g., vascular endothelial growth factor C (VEGF-C) as a transcriptional coactivator by protein–protein interaction." (PMID 34070855, 2021). "However, more specific studies pointed out that, according to the cancer stage, VEGFC plays a differential role." (PMID 34067671, 2021). "Inhibition of VEGFC expression may be beneficial for the treatment of diseases with excess vascularization, such as cancer." (PMID 33875575, 2021). "First, VEGFC mRNA-LNPs cannot integrate into the genome and therefore, there is no risk of genomic instability and cancer formation, which makes it a safe therapeutic modality to use in humans." (PMID 34103491, 2021). "Subcutaneously injected cancer cells form tumors, which in the C1q deficient mice present a disrupted vasculature architecture that could be linked to VEGF-C (vascular endothelial growth factor C) expression." (PMID 33113844, 2020). "This correlation may indicate the potential ability of BACH1 and VEGFC to promote cellular migration and cancer invasion." (PMID 32132179, 2020). "VEGFC/VEGFR2 is an important target for anti-angiogenesis therapy in cancer." (PMID 31892990, 2020). "In addition, overexpression of BACH1 in human ovarian ES2 carcinoma cells induces a significant increase in VEGFC expression, strongly supporting a genetic and functional link between these two factors." (PMID 32132179, 2020). "Vascular endothelial growth factor-C (VEGF-C) is important in cancer metastasis as well." (PMID 31505740, 2019). "We saw increased VEGFC secretion by cancer cells in response to docetaxel treatment." (PMID 29976154, 2018). "Other molecules have also been reported to control the VEGFC levels in cancer." (PMID 29717026, 2018). "As with TNBC, in these cancers, increased expression of VEGFC correlates with poorer prognosis." (PMID 29976154, 2018). "Isolating the cancer cell macroscopically from the lymph node environment might deprive cancer cells of essential survival factors like vascular endothelial growth factor-C/D and plateled derived growth factors." (PMID 28704462, 2017). "On the contrary, lymphangiogenesis participates in dissemination of cancer cells by its activation of the growth of lymphatic vessels through the interaction of VEGFC or VEGFD ligands with VEGFR3 receptors expressed at the surface of lymphatic endothelial cells." (PMID 29137669, 2017). "Given that VEGFC could be secreted into the medium by the cancer cells, we thus checked the protein level in the medium." (PMID 27145366, 2016). "Accumulating studies suggest that ASCs like MSCs are capable of promoting angiogenesis through the secretion of growth factors, in particular VEGFC, since angiogenesis is a well-known crucial event for cancer growth, and VEGF secretion plays a pivotal role in this process." (PMID 26060426, 2015). "Of note, a robust induction of FGF10 and VEGFC by AMSCs may require cancer cells with abundant activation of canonical Wnt signaling." (PMID 26060426, 2015). "Together, these results indicate that FGF10 and VEGFC may be candidate paracrine factors responsible for the malignancy of cancer cells induced by Wnt-activated AMSCs." (PMID 26060426, 2015).
cancer (continued). "Based on these assumptions we can then hypothesise that the altered expression of the VEGFC/VEGFR-3 pathway may influence peritoneal diffusion of cancer cells through the lymphatics." (PMID 22808003, 2012). "In recent years, the effect of deletion of the chromosome 10 phosphatase and tensin homolog gene (PTEN), and expression of signal transducer and activator of transcription-3 (STAT3) and vascular endothelial growth factor-C (VEGF-C) have been investigated in malignant tumors." (PMID 23170117, 2012). "Notably, the recruitment mechanisms (CCL15 vs CXCL5/CXCL1/8) and effector molecules (VEGFC-dominant vs MMP9/VEGFA-cooperative) display cancer-type specificity, suggesting evolutionary selection for distinct molecular implementations of a conserved TANs-lymphatic metastasis principle." (PMID 40739091, 2025). "Thus, VEGFC appears to be an attractive therapeutic target for cancers." (PMID 35600335, 2022). "Cancer cells are defined as cells expressing high MKI67, CAV1, and CTNNB1 and present spatial variations in the expression of VEGFC, FN1, and NRP1." (PMID 40081369, 2025). "Previous studies have documented the biological and clinical significance of VEGF family members (VEGFA, VEGFB, VEGFC, and VEGFD) in lymphangiogenesis and LN metastasis in various cancer types." (PMID 40492378, 2025). "By regulating angiogenic factors like VEGFC, ELK3 promotes growth of lymphatic vessels, thereby facilitating cancer metastasis." (PMID 39930469, 2025). "PDGFD stimulation of CAFs increases VEGFC and VEGFA secretion, which recruits LECs expressing VEGFR2 and VEGFR3, enhancing lymphatic vessel permeability and facilitating cancer cell migration across the lymphatic endothelium." (PMID 40173050, 2025). "Recently, CNTN1 has been reported to mediate cell functions involving multiple signaling pathways, including the Notch signaling pathway, RHOA dependent pathway, RET/PTC3 pathway, and VEGFC/FLT4 axis to promote the invasion and metastasis of cancer cells." (PMID 38562021, 2024). "The angiogenesis markers VEGFA, VEGFC and VEGFD were expressed in the cytoplasm of the cancer cells." (PMID 39557919, 2024). "Although VEGFC, a lymphangiogenic VEGF, has been demonstrated to induce the metastasis and progression of various types of cancers, there are few reports showing its direct role in intercellular adhesion." (PMID 36766725, 2023). "In a lung cancer model, high levels of VEGFC (and VEGFD) promote cancer cells spread to regional lymph nodes and tumor lymphangiogenesis, facilitating lymphatic metastasis, including dissemination of cancer cells into the pleural space." (PMID 35336793, 2022). "VEGFC is a major ligand for VEGFR3, which induces receptor phosphorylation and activation of its downstream signaling pathway in human tissues and cancers." (PMID 36336681, 2022). "Considering the striking therapeutic value of targeting NRPs for both models of cancers, we first analyzed the relative expression of NRPs and their ligands VEGFA and VEGFC on a panel of cell lines available in the TCGA data base." (PMID 33461580, 2021). "We also noticed that growth factors, including NOV, BMP4, MDK, GDF15, VEGFC, NTF3, and LIF, were previously reported to promote cancer development, especially in cancer metastasis in various cancers, including CRC." (PMID 34440086, 2021). "EPO directly increases the vascular angiogenesis of cancer cells and EPO increases the macrophage secretion of VEGFC, then increases lymphangiogenesis and nodal metastasis." (PMID 32908942, 2020). "VEGFC and its receptors VEGFR2 and VEGFR3 play important roles in cancer development and metastasis." (PMID 31892990, 2020).
cancer (continued). "We furthermore discovered 5 genes (MDGA1, VEGFC, MCM10, CTBP1-DT, CHMP4A) with three OS correlations, and 22 genes with two OS correlations, across eight cancer types." (PMID 32764426, 2020). "Taken together, our findings indicated that lncRNA HUMT promotes cancer cell proliferation, lymph node metastasis, and lymphangiogenesis by HUMT/YBX1/FOXK1-mediated Akt/mTOR and VEGFC signaling." (PMID 32138762, 2020). "In the lymphangiogenic pathway, the VEGFC–VEGFR3 and VEGFD–VEGFR3 axes are required for the dissemination of cancer cells to systemic lymph nodes and distant organs." (PMID 30148861, 2018). "In this study, we found that OCT4 enhances vascular endothelial growth factor C (VEGF-C) promoter activity to promote VEGF-C expression and activates VEGF receptor 3 (VEGFR-3) in ECC cells, thereby inducing cancer cell epithelial-mesenchymal transition (EMT)." (PMID 29069758, 2017). "It processes many cancer-related proteins like IGF1R, the vascular endothelial growth factor C (VEGF-C) or the membrane-type 1 matrix metalloprotease (MT1-MMP)." (PMID 27572312, 2016). "Signaling through vascular endothelial growth factor C (VEGF–C) andVEGF receptor 3 (VEGFR-3) plays a central role in lymphangiogenesis and themetastasis of several cancers via the lymphatics." (PMID 24708522, 2014). "Body-wide expression profiles for EPHA2, VEGFC, and ERBB3 indicated the most selective overexpression in malignant connective tissues, when compared to all other pediatric cancer and healthy normal tissues." (PMID 23227212, 2012). "Nevertheless, the differential expression of EGFR and VEGFc, in addition to MMP9 and CXCL5, differentially packaging into IRF5-low versus IRF5-high EVs across two cancer types provide insight into the mechanisms by which IRF5 contributes to protection from PMN formation." (PMID 38969706, 2024). "Although NMUR1 expression was comparable in patients with or without metastasis, its level was significantly increased in cancers with lymph node invasion and correlated with increased expression of VEGFC (vascular endothelial growth factor C), an inducer of lymphangiogenesis." (PMID 36482448, 2022). "Moreover, CNTN1 was identified as a direct downstream molecule of the vascular endothelial growth factor C (VEGFC)-VEGF receptor 3 (VEFGR3)/fms-related tyrosine kinase 4 (Flt4) axis important in lymphangiogenesis and lymphatic invasion in cancers." (PMID 32752094, 2020). "In contrast to CEACAM5 and CXCL17, two markers demonstrated lower levels in the plasma of cancer patients: VEGFR2 acts as a cell-surface receptor for vascular endothelial growth factors (VEGFA, VEGFC and VEGFD), and is involved in angiogenesis in both physiological and pathological conditions." (PMID 31357969, 2019). "In addition, it also inhibits VEGFR-3, VEGFC, and CD31, and provides protection against cancer growth." (PMID 30871059, 2019). "The signaling transduction protein VEGFC could be translocated to the nucleus in early-stage and late-stage PTC to promote lymphomagenesis and cancer cell proliferation." (PMID 31126066, 2019). "Moreover, the levels of VEGFC and lymphatic endothelial cell marker LYVE-1 expression were also up-regulated in the cancer tissues." (PMID 29717026, 2018). "Fifteen members of cancer pathways, including FOS, TGFα, FZD8, MMP1, laminin subunit gamma 2, PTGS2, laminin subunit beta 3, ITGA2, laminin subunit alpha 3, VEGFC, WNT2B, heat shock protein 90 beta family member 1, WNT5B, FGF5 and WNT3A, were up-regulated in the MC group." (PMID 30482199, 2018). "Indeed, the Wnt signaling of AMSCs was activated when they were co-cultured with cancer cells; sequentially the Wnt-activated AMSCs increased their expressions of EMT genes, including FGF10, VEGFC, MMPs, and cytokines." (PMID 26060426, 2015).
cancer (continued). "Indeed, extracellular signaling of FGF10, VEGFC, IL10 and TNFα of AMSCs was dramatically induced when they were co-cultured with cancer cells, and these molecules are suggested to have a direct or indirect impact on Wnt signaling pathway." (PMID 26060426, 2015). "Reducing M2 macrophage characteristics systemically may provide advantages to cancer patients because they express much lower levels of TGFβ, VEGFA, VEGFC, MMP-9, and MMP-1." (PMID 23667623, 2013). "To investigate whether SREBP1 and SREBP2 involved in SOAT1-mediated lymphangiogenesis and VEGFC production, we pharmacologically inhibited SREBP1 and SREBP2 by fatostatin, which displays antitumor activity in cancers by downregulating SREBP- mediated metabolic pathways." (PMID 34790132, 2021). "VEGFC and VEGFD bind to VEGFR3 and activate the downstream signals, which may induce lymphangiogenesis and promote lymph node and organ metastasis in various cancers." (PMID 33128283, 2021). "Together, these observations suggest that Wnt signaling pathway may play a unique role in activation of both VEGFC and FGF10 signaling, highlighting that an activation of Wnt signaling may be a potential common effect for AMSCs in response to Wnt-activated cancer cells in multiple settings." (PMID 26060426, 2015). "VEGFC and TNFB were expressed at low levels in NPC but high levels in most of the non-NPC cancer types." (PMID 35439170, 2022). "The significant decrease in cancer cell death after treating with docetaxel in both MDA-MB-231 and HCC38 cell lines was dependent on the presence and number of LECs, but not directly on VEGFC/VEGFR3 signaling." (PMID 29976154, 2018).
infection (12 papers, 2009 to 2026). The state of being infected such as from the introduction of a foreign agent such as serum, vaccine, antigenic substance or organism. "The expression of FLT4 and VEGFC is increased in macrophages after infection, and FLT4 signaling was found to be important in affecting key cellular processes, such as autophagy, inflammasome activation, and pyroptosis, all of which contribute to successful bacterial clearance." (PMID 39600882, 2024).
adenocarcinoma (10 papers, 2006 to 2020). A common cancer characterized by the presence of malignant glandular cells. "In the GC sample cohort from the TCGA (Stomach adenocarcinoma (TCGA, Firehose Legacy, n = 478)), the levels of several markers for macrophages (FN1, MRS1, CD68, and CCL7), blood vessels (CDH5) and lymphatic vessels (VEGFC) exhibited positive correlations with TGM2 expression." (PMID 32467608, 2020).
kidney disease (6 papers, 2019 to 2025). "VEGFC is central to lymphangiogenesis in kidney disease and triggers lymphangiogenesis primarily through the activation of VEGFR3." (PMID 38693148, 2024).
neurological disease (4 papers, 2022 to 2024). "Vascular endothelial growth factor-C (VEGF-C) regulates MLV development and maintenance and has therapeutic potential for treating neurological disorders." (PMID 38442272, 2024).
VEGFC also shares sentences with these, for which no sentence is quoted: squamous cell carcinoma (14 papers); metabolic syndrome (12); head and neck cancer (10); diabetes (9); gastric adenocarcinoma (9); metastatic melanoma (7); cardiovascular disease (6); lymphoma (6); type 2 diabetes (6); angiosarcoma (5); Cognitive impairment (5); diabetic foot ulcer (5); ischemic stroke (5); neuroblastoma (5); ovarian tumors (5); benign tumors (4); brain injury (4); Chronic colitis (4); chronic kidney disease (4); inflammation (4); invasive breast carcinoma (4); Lewis lung carcinoma (4); metabolic disorders (4); sarcoma (4); acute kidney injury (3); Anxiety (3); arteriosclerosis (3); brain disease (3); clear cell renal cell carcinoma (3); dry eye (3).
A further 213 diseases each share a sentence with VEGFC in 3 papers or fewer.